BAG1 (BAG cochaperone 1)
Diseases named in the same sentence as BAG1 in open-access papers (continued):
Sharing a sentence is not in itself a finding about the gene and the disease.
tumor (continued). "The identification and further characterization of these clients of the HSP70/BAG1 complex provides the initial step towards targeted therapies that can convert MYC from a pro-tumorigenic oncogene to a pro-apoptotic tumor suppressor." (PMID 30902071, 2019). "We observed that both Ser136 and Ser112 phosphorylation were significantly increased in tumor cells, in line with the observed increased levels and activities of Bag-1, Akt, and Raf in tumors." (PMID 31883527, 2019). "This study identified a potential biomarker, Bcl-2 associated athanogene-1 (BAG-1), that is implicated in HNSCC insensitive to cisplatin and tumor progression." (PMID 28877725, 2017). "A strong inverse correlation was found between nuclear BAG-1 expression and tumour size, whereas ERα and PgR expression moderately correlated with nuclear and (to a lesser extent) with cytplasmic BAG-1 expression." (PMID 28510570, 2017). "Although the intensity and cytoplasmic/nuclear localisation of BAG-1 protein immunoreactivity has been related to tumour grade, disease subtype and clinical outcome, both positive and negative correlations with survival have been described." (PMID 28510570, 2017). "As expected, we found that gene expression patterns are different in PC tumor samples compared to normal, undiseased peritoneum with a number of genes differentially regulated: BAG1, CCNB1, CD44, CLDN4 and 6, MMP2, MKI67, MUC1, MYBL2, and SERPINB3." (PMID 27542596, 2016). "The results from the present study showed that miR-138 has a tumor suppressing function through regulation of its target gene Bag-1." (PMID 25962180, 2015). "Cox multivariate analysis revealed that tumor differentiation, clinical stage as well as BAG-1 expression were independent prognostic factors for survival in patients with NSCLC." (PMID 22179630, 2012). "Our finding that the Bag-1 peptide interacts with the substrate-binding domain of GRP78/BiP further opens the possibility for external application of this peptide for tumor therapy." (PMID 23049684, 2012). "The Bag-1 peptide we have shown to inhibit tumor cell growth consists N-terminally of twenty amino acids that form an extended loop and a β-sheet of the ubiquitin-like domain (1WXV.pdb), followed by helix 1 of the BAG domain (1I6Z.pdb)." (PMID 23049684, 2012). "In the present study, elevated BAG-1 expression was found in the tumor tissues of patients with NSCLC." (PMID 22179630, 2012). "The 20/60 epidermal SCC sections that showed strong Hsp70 staining highlighted a subset of tumours with moderate to strong cytoplasmic Bag-1 expression." (PMID 21522149, 2011). "Most tumours showed reduced nuclear Bag-1 staining, but a subset exhibited strong Bag-1 staining, with cytoplasmic Bag-1 staining intensity correlating with cytoplasmic Hsp70 staining intensity (rs=0.462; P<0.001) and less differentiation (P<0.001)." (PMID 21522149, 2011). "The overall picture is of reduced intensity of nuclear Bag-1 staining in the tumours compared with normal skin epithelium." (PMID 21522149, 2011). "Reduced nuclear staining intensity compared with normal epithelium is a feature of most tumours, whereas a subset showed high levels of Bag-1 throughout the cells, particularly noticeable as strong cytoplasmic staining." (PMID 21522149, 2011). "The basal layer of epidermis adjacent to the tumours frequently showed much reduced nuclear Bag-1 staining compared with normal epithelium; however, elevated Bag-1 expression was seen to co-localise with Hsp70 expression in the rete pegs (data not shown)." (PMID 21522149, 2011). "There was also a weak correlation between the percentage of cells that stained positively for Hsp70 in the tumours and the percentage that were positive for Bag-1 (P=0.027; correlation coefficient=0.286)." (PMID 21522149, 2011).
tumor (continued). "Within ER-positive tumours (n=189), high nuclear BAG-1 expression was an independent predictor of outcome in both univariate and multivariate analyses." (PMID 19066611, 2009). "One way to reduce BAG-1 expression is through use of RNA interference-based gene silencing, in particular as BAG-1 overexpression has been observed in human tumours." (PMID 15560850, 2004). "This study identifies BAG-1 as a protein specifically required at wild type expression levels for the survival of tumour cells and reveals it as potential anticancer target." (PMID 15560850, 2004). "Tumor area was reduced by 75% in 4 month lungs of BAG-1 haploinsufficient mice compared to mice with two BAG-1 copies." (PMID 15560850, 2004). "The percentage of tumours exhibiting nuclear BAG-1 positivity was significantly higher in cases positive for distant metastases (55.6%) compared to cases without distant metastases (20.8%; P=0.036; Fisher's exact probability)." (PMID 12402153, 2002). "BAG-1L-specific antibodies will be useful in analysing the expression of specific BAG-1 isoforms in tumour samples." (PMID 12373595, 2002). "BAG-1 was readily detected by immunostaining in normal breast epithelial cells and most ER-positive tumours, but was undetectable or weakly expressed in ER-negative tumours." (PMID 10576663, 1999). "The opioidergic system is also regulated by GR activation, indicating that melatonin and BAG-1 regulation of the GR will modulate the opioidergic system as well as wider physiological processes relevant to the intercellular interactions in the tumor microenvironment." (PMID 37970210, 2023). "Moreover, miR-28-5p was found as a tumor suppressor directly targeting and deregulating Bag-1 in B cells." (PMID 37533517, 2022). "Tumours collected from mice at diestrus exhibited a significant increase in the expression of genes Mki67 (p = 0.05), Ccnb1 (p = 0.02), Erbb2 (p = 0.03), Grb7 (p = 0.02), and Bag1 (p = 0.05), compared to tumours collected at estrus." (PMID 34174867, 2021). "For example, BAG1 participates in various biological functions such as signal pathways, cellular proliferation, apoptosis, transcription, differentiation, embryogenesis, and neoplasia." (PMID 32678057, 2020). "The identification of these HSP70/BAG1 chaperone clients introduces new targets that could be therapeutically exploited to disrupt the survival of tumor cells driven by MYC activation." (PMID 30902071, 2019). "The authors reasoned that weak nuclear BAG-1 expression observed in this cohort may be due to the presence of a high proportion (58%) of poorly differentiated tumours." (PMID 28510570, 2017). "Moreover, patients whose tumours had high nuclear BAG-1 expression had a trend towards shorter disease-free and overall survival." (PMID 28510570, 2017). "Interestingly, the anti-apoptotic gene BAG1 appeared to be slightly diminished (less than 2-fold) in the tumor sample population." (PMID 27542596, 2016). "Enhanced expression of BAG-1 was also detected in tumor samples obtained from patients with NSCLC." (PMID 22179630, 2012). "Effect of the Bag-1 peptide on tumor weights in 22Rv.1 and LNCaP xenograft tumor mouse models." (PMID 23049684, 2012). "We could also show that the Bag-1 peptide decreases tumor cell growth in vivo in two models of tumor xenografts (22Rv.1 and LNCaP)." (PMID 23049684, 2012). "Some tissues and tumour cells express a fourth Bag-1 isoform, 29 kDa in size." (PMID 21522149, 2011). "However, examining the series of tumours further, there was an inverse association between SCC differentiation and intensity of cytoplasmic Bag-1 staining in the sections (P<0.001)." (PMID 21522149, 2011). "Overall, tumours showed reduced levels of nuclear Bag-1 compared with normal epidermis." (PMID 21522149, 2011).
tumor (continued). "Our data suggest that further study is warranted to address the hypothesis that cytoplasmic Bag-1 and Hsp70 expression together may identify tumours that are more likely to progress and potentially metastasise, as well as acquire resistance to chemotherapy." (PMID 21522149, 2011). "Further investigation of Bag-1 function will be important, as the Bag-1:Hsp70 complex may be an appropriate target to sensitise tumour cells to apoptosis-inducing agents and overcome resistance to chemotherapy." (PMID 21522149, 2011). "This may reflect an increase in both nuclear and cytoplasmic Bag-1 expression in the poorly differentiated tumours." (PMID 21522149, 2011). "One plausible explanation is that poorly differentiated tumors depend on other prosurvival pathways, and decreased Bcl-2 and Bag-1 expression is merely a marker of aggressive tumor behavior rather than mechanistically associated with aggressive biology." (PMID 18430249, 2008). "Reduced BAG-1 expression specifically targets tumor cells to apoptosis and impairs tumorigenesis." (PMID 15560850, 2004). "Since many key components of survival pathways are regulated by interaction with (co-)chaperones, our finding is not without precedent but novel insofar as we have uncovered that reduced BAG-1 expression specifically targets tumour cells to apoptosis and impairs tumorigenesis." (PMID 15560850, 2004). "We examined BAG-1 expression by immunohistochemistry in paired samples of primary tumour and matched lymph node metastasis and demonstrated statistically significant increased cytoplasmic expression in 8 of the 13 metastatic tumours relative to the corresponding primary tumour (P=0.021)." (PMID 12373595, 2002). "Multiple alterations contribute to carcinogenesis, and tumours that counter apoptosis by overexpressing Bcl-2 and/or BAG-1 might represent one class of tumours." (PMID 12373595, 2002). "Moreover, BAG-1L protein is rarely expressed in normal tissues but is commonly expressed by tumour cell lines, and a change in BAG-1 mRNA translation frequently accompanies malignant transformation." (PMID 12402153, 2002). "Whether this would indicate that the upregulation of endogenous mitochondrial melatonin in tumors suppresses the protection afforded by BAG-1 in tumors will be important to determine, including how this would impact the prosurvival effects of the GR in tumor cells." (PMID 37970210, 2023). "Bag proteins like Bag1 and Bag3 have been implicated in tumor growth and survival but it is not known whether Bag5 also exhibits this function." (PMID 23448667, 2013). "However, a subset of tumours showed moderate to strong Bag-1 staining." (PMID 21522149, 2011). "This group of patients has a strong positive correlation with a luminal A phenotype and low histological grade, which suggests that BAG-1 may be a useful surrogate marker of intact ER signalling and identifies those tumours maintaining a luminal A-differentiated phenotype." (PMID 19066611, 2009). "Thus, nuclear BAG-1 expression may indicate either high levels of BAG-1L or relocalisation of BAG-1S or BAG-1M to the nucleus in response to specific signals in the tumour microenvironment." (PMID 12373595, 2002). "The small isoform of BAG1, BAG1S, in cooperation with the HSP70 chaperone complex, selectively mediates cell survival in MYC overexpressing tumor cells." (PMID 30902071, 2019). "The small isoform of BAG1, BAG1S, in cooperation with the HSP70 chaperone complex, promotes cell survival in MYC overexpressing tumor cells." (PMID 30902071, 2019). "We report here that a single isoform of BAG1, termed BAG1S, is responsible for the survival of tumor cells with elevated MYC." (PMID 30902071, 2019).
tumor (continued). "For example, FOXA1, MLPH, NAT1, MAPT and BAG1 are expressed in luminal tumours according to published mRNA profiles and also co-clustered in our data, with higher expression levels in most ERPR tumours." (PMID 26725330, 2016). "Upregulation of anti-apoptotic genes, including BAG1, BCL11B and SERPINB2, and downregulation of apoptotic genes, such as DAPK2, HRK and TP53INP1, can promote tumor cell survival." (PMID 23024765, 2012). "In the multivariate model employed, which incorporated standard pathological indicators of outcome: tumour size, grade, nodal status, PR and HER-2, the resolved model, which eliminates redundant variables, retained HER-2, PR and BAG-1." (PMID 19066611, 2009). "Thus, BAG-1 overexpression provides a potential mechanism by which tumours lacking oncogenic RAS mutations might activate MAP kinase pathway mediated proliferative and survival signals." (PMID 12373595, 2002). "A strong relationship between nuclear BAG-1 expression and tumour grade/differentiation has been identified in two studies, with relatively high levels of nuclear BAG-1 expression in low grade tumours." (PMID 12373595, 2002). "In this study, we found significantly higher Bag-1 levels in tumor tissues compared to normal tissues independent of the tumor’s receptor status." (PMID 31883527, 2019). "Assay controls comprised specimens incubated with secondary but no anti-BAG-1 primary antibody or tumour sections that exhibited no BAG-1 immunoreactivity." (PMID 28510570, 2017). "Tumor and non-tumor samples differed significantly in the expression of 10/22 genes: CCNB1, CLDN4, CLDN6, MMP2, MUC1 (all: p < 0.05), BAG1, SERPINB3 (all: p < 0.01), CD44 (standard variant), MKI67, and MYBL2 (all: p < 0.001)." (PMID 27542596, 2016). "ERCC1 and BAG-1 are determinants of survival after surgical treatment of NSCLC, and its mRNA expression in tumor tissues could be used to predict the prognosis of NSCLC treated by platinum." (PMID 22439756, 2012). "Overexpression of Bag-1 and Hsp70 in poorly differentiated SCC may confer both enhanced tumour cell growth and apoptosis resistance." (PMID 21522149, 2011). "In vivo, tumours are heterogeneous for Bag-1 expression and the intensity scores reflect the majority of the tumour rather than the maximal intensity of staining." (PMID 21522149, 2011). "Overall, the tumours showed no change in cytoplasmic Bag-1 staining intensity compared with normal epidermal epithelium." (PMID 21522149, 2011). "Interestingly, an expression profiling study of pre-treatment biopsies from 40 patients treated with AC chemotherapy identified BAG-1, BCL-2 and ER among a diverse group of 178 genes overexpressed in sensitive tumours." (PMID 19066611, 2009). "Overall survival was significantly shorter for patients with tumours exhibiting BAG-1 positive nuclei than those with absent nuclear BAG-1-staining (P=0.011)." (PMID 12402153, 2002).
tumor (continued). "We did, however, observe a tendency for patients with nuclear BAG-1 expression to have slightly (but not statistically significantly) improved outcomes, consistent with the correlation we found with low tumour grade." (PMID 12373595, 2002). "Survival at 5 years was 51.3% in patients with tumours exhibiting nuclear BAG-1 positivity compared to 83.9% in those patients with tumours that were negative for nuclear BAG-1 staining." (PMID 12402153, 2002). "There was significant variation in the immunohistochemical staining patterns of BAG-1 with tumours exhibiting absent staining and staining of either the cytoplasm, nucleus or both." (PMID 12402153, 2002). "In addition, these CENPF-related genes exhibited the expression differences between normal and tumor tissues: the expression of TOP2A or KIF23 was significantly upregulated in LPS, while that of BAG1,PNPLA2, CRYL1 or GRN was significantly downregulated in LPS or MRCLPS compared to normal tissues." (PMID 37108172, 2023). "Consequently, the F2P Score was established based on the combination of six genomic variables (ESR1, PGR, CD68, BAG1, BCL2, and GSTM1) and two clinicopathological variables (age and categorical tumor size) with the shrinkage factors of 0.314 and 0.888, respectively." (PMID 33042787, 2020). "In univariate analysis, nuclear BAG-1 staining was correlated with worse prognostic indicators (stages III–IV, tumour size >5 cm and presence of four or more positive lymph nodes) compared to cytoplasmic staining (stage II, tumour size 2–5 cm and one to four positive lymph nodes)." (PMID 28510570, 2017). "However, the involvement of BAG-1 in the tumor development and chemotherapy in NSCLC patients has not been clarified." (PMID 22179630, 2012). "In addition, the prognosis of patients with nuclear BAG-1-positive tumours was significantly worse than that of those with nuclear BAG-1-negative tumours." (PMID 12402153, 2002). "Similarly, the Naderi cohort also showed positive associations between high BAG-1 expression and ER+ (P=0.0014), HER-2 negativity (P=0.0044) and low histological grade (P=0.0061) but not with tumour size or lymph node status (P=0.081 and P=0.106, respectively)." (PMID 19066611, 2009). "So, in this study, we use RT-PCR to examine the expression of ERCC1, BAG-1, BRCA1, RRM1 and TUBB3 in tumor samples from patients with resected NSCLC not receiving adjuvant chemotherapy." (PMID 22439756, 2012). "However, hormone-related genes (BAG1, BCL2, CD68, ESR1 (ER), GSTM1, PGR, SCUBE2) do not show significant differential expression among all tumor samples." (PMID 38254834, 2024).